CDK2 (cyclin dependent kinase 2)
Diseases named in the same sentence as CDK2 in open-access papers (continued):
Sharing a sentence is not in itself a finding about the gene and the disease.
glioblastoma (continued). "The mechanism by which TMZ induces senescence in glioblastoma cells is thought to be by upregulation of p21 and inhibition of CDK2." (PMID 17968428, 2007). "However, the exploration and application of a CDK-2 inhibitor in the treatment of glioblastoma are sparse." (PMID 38184514, 2024). "Thus, there is an important new interaction—METTL3/ADAR1/CDK2—as a potential target for glioblastoma therapy." (PMID 36012529, 2022). "Our study suggests that NSC139021 may be a potential chemotherapy drug for the treatment of glioblastoma by targeting the Skp2-p27/p21-Cyclin E/CDK2-pRb signaling pathway." (PMID 34572430, 2021). "During large-scale sequencing to identify mutations in protein kinases in human cancer cells and primary tissue, we identified a heterozygous missense mutation in the cdk2 gene in a short-term culture of a glioblastoma (data not shown)." (PMID 20399812, 2010). "In glioblastoma (GBM), CDK2 expression is significantly enriched and functionally required for tumor proliferation." (PMID 39800748, 2025). "Moreover, a CDK2 inhibitor also attenuated tumour glioblastoma growth in vitro and in vivo." (PMID 38732271, 2024). "In glioblastoma, ADAR1 elevates CDK2 expression by binding to CDK2, while METTL3 upregulates ADAR1 protein expression and promotes G1/S phase transition." (PMID 37996892, 2023). "Overexpression of WTAP facilitates renal cell carcinoma by stabilizing CDK2 transcript, and WTAP promotes the invasiveness of glioblastoma through enhancing the activity of EGFR." (PMID 36855062, 2023). "CDK2, which is often upregulated in GBMs compared to normal brain tissue, has been shown to be downstream EGFR target in glioblastoma cell lines." (PMID 37936247, 2023). "The small masses developed by shADAR1 cells were also less proliferative compared to the mass originated from the control glioblastoma cells, as shown by Ki67 staining, and exhibited a significant decrease of ADAR1 and CDK2 protein expression." (PMID 33509238, 2021). "A recent study conducted on a human glioblastoma cell line showed that protein kinase C- (PKC-) ι phosphorylates CDK7 at Thr170 and CDK2 at Thr160." (PMID 23840966, 2013). "However, CDK2 and CDK4 were positively correlated with tumor purity in skin cutaneous melanomas, LUADs, LIHCs, head and neck cancers, glioblastomas, and breast invasive carcinoma." (PMID 33668805, 2021). "However, CDK2/CDK4 and CDK6 expressions were negatively correlated with immune infiltration in glioblastomas and skin cutaneous melanomas." (PMID 33668805, 2021). "Similarly, the flavonoid phloretin increased the production of reactive oxygen species and dose-dependently decreased the expression of CDK2, CDK4, and cyclin D to ultimately inhibit the proliferation of human glioblastoma cells." (PMID 33321738, 2020). "Expression levels of Cyclin-Dependent Kinase (CDK-1, CDK-2, and CDK-6) were also significantly down-regulated in U87TRAF3IP2KD cells (-9.3, -2.4, and -2.1, respectively), indicating that silencing TRAF3IP2 affects glioblastoma cell cycle progression." (PMID 30038719, 2018). "The qRT-PCR results confirmed the down-regulation of the mitotic cell cycle regulators such as CDK2 and SMC4 in both lung and glioblastoma SOX2OT knocked down cancer cell lines, while the CDK2AP2 which is also known to interact and inhibit CDK2, is up-regulated more than two times in treated cells." (PMID 30202240, 2018). "However, there was no consistent pattern of changes in the levels of p27 and CDK2 in the glioblastoma cells." (PMID 27852054, 2017).
bladder cancer (40 papers, 2013 to 2025). "In bladder cancer, an increased level of CDK2 was associated with an advanced tumour stage and grade." (PMID 38732271, 2024). "This escape from checkpoint activation occurs more easily in cells with a high level of active CCNE/CDK2 and is favored by deficiencies in G1 checkpoint control like those prevalent in bladder cancer." (PMID 33670166, 2021). "Enhanced activity of the cdk2-cyclin A axis is also closely associated with bladder cancer proliferation with alterations of the cdk2 network as a key event during the process of resistance acquisition." (PMID 31167517, 2019). "Protein and mRNA analyses of bladder carcinoma tissues have indicated that cdk2 is closely associated with bladder tumor development and progress." (PMID 25136960, 2014). "Then, we performed WB experiments on bladder cancer cell lines with knockdown or overexpression of IGF2BP3 to investigate the expression changes of multiple cyclin proteins CDK2, CDK4, CDK6, and CCND1." (PMID 40083693, 2025). "Mistletoe from Salicis specifically targeted CDK1 and 2, and Cyclin A, whereas mistletoe from Populi acted via CDK2 and Cyclin A and B. Low-grade bladder cancer appears to be more sensitive to mistletoe extracts than high-grade bladder cancer." (PMID 37835543, 2023). "In bladder cancer, expression of CDK2 has been increased, while expression of a CDK2-targeting miRNA, namely miR-3619 has been decreased." (PMID 36266723, 2022). "Another experiment in an animal model of bladder cancer has shown the anticancer role of Cdk2 activation in palbociclib-treated animals, indicating that the anticancer effect of palbociclib is exerted via Cdk2 activation." (PMID 36266723, 2022). "The Cdk4/6 inhibitor palbociclib has been shown to exert antitumor effects against bladder cancer cells through modification of Cdk2." (PMID 36266723, 2022). "In this respect, our finding suggests that BA led to apoptosis and necrosis in human bladder cancer cells due to partial cell cycle arrest at the sub-G1 phase and G2/M phase via down-regulation of cyclin A, cyclin B1, Cdc2, and Cdk2." (PMID 33806566, 2021). "Further, parthenolide substantially decreases bladder cancer cell viability via G1 phase cell cycle arrest by modulation of CDK2 phosphorylation." (PMID 33996570, 2021). "Down-regulation of CDK2, cyclin A, cyclin B1 and cyclin E contributed to the anti-proliferation effect of apigenin treatment in human bladder cancer T-24 cells." (PMID 33959508, 2021). "In terms of the interaction of miRNAs and circRNAs that are upstream of CDK2, it was reported that by downregulating miR-3619-5p, CDK2 exerted a crucial role in promoting the proliferation, migration and invasion of bladder carcinoma cells." (PMID 32699532, 2020). "In the current experiments, knocking down cdk2 or cyclin A led to a substantial reduction of the tumor cell number, indicating the clinical relevance of both proteins for bladder cancer." (PMID 25136960, 2014). "Treatment of bladder cancer cells with propofol could inhibit their proliferation and enhance cell apoptosis through regulation of CDK2 expression." (PMID 36266723, 2022). "In addition, amygdalin, a natural compound, efficiently inhibited the growth of bladder cancer cells in vitro through diminishing cyclin A and cdk2." (PMID 35293283, 2022). "Moreover, suppression of CDK2 can partly reverse the impacts of miR-340 inhibition on proliferation and apoptosis of propofol-treated bladder cancer cells." (PMID 36266723, 2022). "Cycle arrest at G0/G1 transition in human bladder cancer cells may have been due to the enhanced of expression of p21 with a decrease in cyclin E1, CDK2, and CDK4 kinase levels." (PMID 31024833, 2019). "From our present data, we postulate that VPA might reverse bladder cancer cell therapy resistance to temsirolimus by at least partially blocking the cdk2/cyclin A axis." (PMID 29299126, 2017).
bladder cancer (continued). "Since cdk2 reduction was paralleled by a p27 decrease in the bladder cancer model, it seems likely that amygdalin not only acts on tumor growth but could also influence metastatic spread." (PMID 25136960, 2014). "Indeed, although cdk2-cyclin A are altered in many solid tumors, information about cdk2-cyclin A in bladder cancer is sparse." (PMID 25136960, 2014). "In bladder cancer, Apigenin inhibited the proliferation of T24 cells, blocking cell cycle progression at the G2/M checkpoint through an increase in p21 and p27 protein levels and a decrease in Cyclin A, Cyclin B1, Cyclin E, cyclin-dependent kinase-2 (CDK2), Cdc2, and Cdc25C levels." (PMID 38791608, 2024). "Furthermore, network analysis of significantly altered proteins in bladder cancer revealed CDK2 as one central regulator mediating cisplatin resistance, with the consequence that targeting the CDK–cyclin axis may restore cisplatin-sensitivity." (PMID 36232303, 2022). "METTL3 is known to promote cell cycle progression in cancers like HNSCC and bladder cancer and it regulates cell cycle markers such as CDK2 (cyclin-dependent kinase 2) and Cyclin D1 in gastrointestinal stromal tumors." (PMID 40338154, 2025). "IGF2BP3-mediated mRNA stability of multiple oncogenes, such as CDK2 and STAT3 via a m6A-dependent manner, have been found to promote the development of bladder cancer." (PMID 39680264, 2024). "In bladder cancer, KNSTRN affects the cell cycle by regulating the expression of cyclin D1 and CDK2." (PMID 38198023, 2024). "The top most enriched clinical phenotypes in CDK2/4/6 PPI networks are head and neck cancer, leukemia, bladder carcinoma, vitrities, and small cell lung cancer." (PMID 33668805, 2021). "Morin decreases CDK2, CDK4, cyclin D1, and cyclin E via modulation of the p21/WAF1 pathway, suppressing c-Jun N-terminal kinase (JNK) and AKT phosphorylation, and preventing MMP-9 expression by repressing NF-κB, SP-1, and AP-1 in EJ bladder cancer cells." (PMID 33996570, 2021). "Additionally, p21WAF1 level in CDK2 and CDK4 complexes in MSSV-treated bladder cancer cells was higher than that in the untreated cells." (PMID 33430488, 2021). "p27KIP1 level associated with CDK2 and CDK4 also increased in both MSSV-treated bladder cancer cells as opposed to the untreated cells." (PMID 33430488, 2021). "Similarly, another study also reported decreased expression levels of cyclin D1, cyclin E, CDK2 and CDK4 in bladder cancer cells in a dose-dependent manner (0, 25, 50, 100 μg/mL) after 24 h of fucoidan treatment (undefined species source)." (PMID 32046368, 2020). "Decreased p-Cdk2 and Cyclin A were observed in ACT-treated bladder cancer cells." (PMID 29348843, 2017). "In addition, analysis of TCGA expression data via gene expression profiling interactive analysis (GEPIA) demonstrated that CDK1, cyclinA2 and cyclinB1 are observed at increased expression levels in bladder cancer tissues, whereas CDK2, CDK4 and cyclinD1 are not differentially expressed." (PMID 40518827, 2025). "Knockdown of GAS5 significantly increases CDK6 mRNA and protein levels in bladder cancer cell lines, but downregulation of GAS5 don’t change CDK2 and CDK4 expression level (data not shown)." (PMID 24069260, 2013). "In addition, it has been reported that MTHFD2 is present in the nucleus and interacts with cyclin-dependent kinase 2 (CDK2), and plays an important role in bladder cancer through non-metabolic functions." (PMID 40280919, 2025).
neuroblastoma (39 papers, 2007 to 2025). Neuroblastoma (NB) is the most common solid, extracranial childhood tumor. "The overexpression of CDK2 in neuroblastoma tissue is associated with poor overall survival, suggesting a potential strategy for patient selection during clinical development of this drug." (PMID 35053461, 2022). "Recently, using systematic time studies of neuroblastoma cell growth, we better defined the G1 arrest caused by iron chelation to a point in mid-G1, where cyclin E protein is present, but the cyclin E/CDK2 complex kinase activity is inhibited." (PMID 25825542, 2015). "PKC-ι promotes cell proliferation in neuroblastoma cells through the PKC-ι/cyclin dependent kinase (Cdk7)/Cdk2 pathway." (PMID 36776326, 2023). "CDK2 was also an independent prognostic factor of paediatric neuroblastoma in the E-MTAB-161, E-MTAB-1781 and GSE85047 datasets." (PMID 35655142, 2022). "CDK2 inhibition suppressed the progression of MYCN-amplified neuroblastoma, and CDK2 antagonists represent potential therapeutic drugs in MYCN-driven neuroblastoma." (PMID 35655142, 2022). "Dinaciclib has shown some activity in MYCN-driven neuroblastoma, attributed to inhibition of CDK2 and CDK9." (PMID 35053461, 2022). "a potent, multiple- cyclin-dependent kinase (CDK) inhibitor has been shown to suppress neuroblastoma growth by inhibiting CDK2 and CDK9 activity." (PMID 33796454, 2021). "Decreased CDK2 protein expression was found in lung and neuroblastoma cells; in fact, CDK2 relative expression of cells treated with 50 μM DHA was approximately 50% less than without DHA treatment." (PMID 28817068, 2017). "SNS-032 (BMS-387032) is a cyclin-dependent kinase 2 (CDK2), 7, and 9 inhibitor under pre-clinical and clinical investigation for a wide range of solid and hematologic malignancies including neuroblastoma." (PMID 27517323, 2016). "In this study, we found that dinaciclib significantly inhibited both anchorage-dependent and independent growth in a panel of neuroblastoma cells by abrogating CDK2 and CDK9 activity." (PMID 27378523, 2016).
neuroblastoma (continued). "CDK2 was also suggested to be an unfavourable prognostic factor for paediatric neuroblastoma." (PMID 35655142, 2022). "By targeting CDK2, miR-885-5p also induced neuroblastoma cell apoptosis and aging." (PMID 34582363, 2021). "CYC065 (fadraciclib), a clinical inhibitor of CDK9 and CDK2 (a major regulator of apoptotic cell death), selectively targets MYCN-amplified neuroblastoma through a loss of MYCN transcription and growth arrest, followed by sensitizing cells for apoptosis as a result of CDK2 inhibition." (PMID 33614505, 2020). "Interestingly, specific CDK2 inhibition is found to be synthetically lethal to MYCN-driven neuroblastoma suggesting a potential role for CDK2-inhibiting drugs also in MB-carrying amplifications in MYCN and perhaps also MYC." (PMID 29511348, 2018). "Both CDK2 and p27Kip1 play an important role in neuroblastoma progression and patient prognosis." (PMID 25594028, 2014). "Notably, p27Kip1 accumulates in neuroblastoma cells treated with retinoids and necessitates neuronal differentiation, whereas increased CDK2 activity correlated with a differentiation blockage." (PMID 25594028, 2014). "Recently, using systematic time studies of neuroblastoma cell growth in vitro with iron chelation treatment, we better defined the G1 arrest to a point in mid-G1, where cyclin E protein is present, but the cyclin E/CDK2 complex activity may be inhibited." (PMID 25825542, 2015). "Higher expression of CCNE1, CDK2 or CHEK2 was an unfavourable prognostic factor, while higher expression of SESN1 was a favourable prognostic factor in paediatric neuroblastoma." (PMID 35655142, 2022). "The Kaplan–Meier survival analysis further showed that overall survival was decreased in paediatric neuroblastoma patients with high CCNE1, CDK2 or CHEK2 expression." (PMID 35655142, 2022). "The results were consistent with overexpression of CCNE1, CDK2 or CHEK2 being worse prognostic factors, while increased regulation of SESN1 was a better prognostic factor in paediatric neuroblastoma." (PMID 35655142, 2022). "In contrast to CCNE1, CDK2 and CHEK2, SESN1 had opposite expression levels and prognostic effects in paediatric neuroblastoma." (PMID 35655142, 2022).